ICAM1 (intercellular adhesion molecule 1)
Diseases named in the same sentence as ICAM1 in open-access papers (continued):
Sharing a sentence is not in itself a finding about the gene and the disease.
dengue (16 papers, 2012 to 2025). "In light of the substantial dengue burden in Sabah and the paucity of genetic studies in this region, investigating the ICAM-1 rs5498 polymorphism offers an important opportunity to better understand host susceptibility factors." (PMID 41313499, 2025). "Although this study demonstrates a significant association between the ICAM-1 rs5498 polymorphism and dengue susceptibility, the findings remain correlative in nature and do not establish a direct causal relationship." (PMID 41313499, 2025). "It is also suggested that a combine host genetic profiling with viral serotyping to be conducted to explore potential serotype-specific effects of ICAM-1 polymorphisms on dengue susceptibility and severity for this population." (PMID 41313499, 2025). "The association between ICAM-1 rs5498 genotypes and dengue risk was further evaluated using logistic regression under recessive and dominant models." (PMID 41313499, 2025). "Increased ICAM-1 expression and elevated soluble ICAM-1 levels have been associated with endothelial activation, enhanced leukocyte adhesion, and greater vascular permeability in severe dengue cases." (PMID 41313499, 2025). "The AST enzyme in dengue patients with warning signs was raised throughout the illness, and this enzyme was associated (i) at the febrile phase- ICAM-1, FGF-Basic, IL-13, IL-4, IL-12 and VEGF; (ii) defervescence: PDGF and (iii) convalescence- IFN-γ and IP-10." (PMID 23284941, 2012). "This upregulation of ICAM-1 is implicated in the pathogenesis of severe dengue, supporting the notion that genetic variations leading to increased ICAM-1 expression, such as the rs5498 G allele, may contribute to disease severity." (PMID 41313499, 2025). "Of note, ICAM-1 polymorphism is associated with dengue disease severity." (PMID 30283445, 2018). "Future studies incorporating genotype-stratified analyses of ICAM-1 gene expression, sICAM-1 serum levels, and in vitro functional assays are warranted to substantiate the biological implications of this variant and to elucidate its precise role in dengue pathogenesis." (PMID 41313499, 2025). "Although only limited studies have directly evaluated this polymorphism, broader evidence supports the involvement of ICAM-1 in dengue pathogenesis." (PMID 41313499, 2025). "In dengue, increased expression of ICAM-1 can result in the consequent influx of cells promoting inflammation of the endothelium." (PMID 34394108, 2021). "Previous studies have reported the roles of HMGB-1 and ICAM-1 in dengue virus infection where both proteins were released by dengue infected endothelium or immune cells and increased permeability of endothelial cells leading to vascular leakage." (PMID 32764789, 2020). "On the other hand, ICAM-1 was expressed significantly higher in dengue cases than in healthy individuals, and the mean concentration was significantly higher in SD patients as compared to DWOWS and DWWS." (PMID 32764789, 2020). "Further assessment of host factors revealed that cytokines such as CCL2, CCL5, CCL20 and CXCL1, as well as adhesion molecule ICAM-1, that are involved in leukocytes infiltration were expressed higher in dengue patients in comparison to healthy individuals." (PMID 32764789, 2020). "The FCPLJ treatment upregulated monocyte chemoattractant protein 1 and downregulated intercellular adhesion molecule 1, integrin beta 3 and fibronectin 1 genes during dengue virus infection." (PMID 30944031, 2019). "Endothelial adhesion molecules, including ICAM-1, appear to be involved in host response to both leptospirosis and dengue." (PMID 24444080, 2014). "Eotaxin, IP-10 and ICAM-1 were significantly higher in secondary infected dengue patients during the febrile phase of illness." (PMID 23284941, 2012). "Furthermore, the FCPLJ treatment has also downregulated the genes associated with the endothelial cell biology (ITGB3, ICAM1 and FN1) that are involved in the endothelial permeability process during dengue virus infection." (PMID 33919457, 2021).
dengue (continued). "Increased levels ICAM-1 have been indicated in endothelium damage and activation, and 75% of the secondary cases in our cohort were of patients with warning signs and/or with severe dengue." (PMID 23284941, 2012). "Several groups have reported endothelial cell activation with high levels of circulating ICAM-1 and VCAM-1 in dengue patients." (PMID 38235130, 2023). "The FCPLJ treatment has affected the regulation of four genes, CCL-2/MCP-1 (upregulated), ITGB3, ICAM1 and FN1 (downregulated), which were involved in endothelial permeability regulation during dengue virus infections." (PMID 30944031, 2019). "The FCPLJ treatment downregulated ITGB3, ICAM1 and FN1 genes, which were upregulated during dengue virus infection." (PMID 30944031, 2019). "Furthermore, it has demonstrated that severe dengue virus infections induce the expression of macrophage migration inhibitory factor (MIF), which in turn stimulates monocytes and endothelial cells to express higher levels of ICAM-1." (PMID 41313499, 2025).
Cognitive impairment (15 papers, 2018 to 2026). Abnormal cognition is characterized by deficits in thinking, reasoning, or remembering. "Additionally, sustained elevation of inflammation-related proteins, including ICAM-1, during the first postnatal month in extremely preterm infants has been associated with increased risk of cognitive impairment at 10 years of age." (PMID 40948499, 2025). "By utilizing a rat model of severe ICAS, early stent placement was found to improve cerebral blood flow, restore blood–brain barrier (BBB) integrity, and alleviate cognitive deficits by downregulating intercellular adhesion molecule 1 (ICAM1) expression." (PMID 41404041, 2025). "Recent studies have shown that, animals subjected to chronic cerebral hypoperfusion upregulates intercellular adhesion molecule 1 (ICAM-1) and vascular adhesion molecule 1 (VCAM-1) in the vascular ECs that was associated with cognitive impairment." (PMID 38300642, 2024). "Specifically, increased CSF levels of ICAM-1, IL-8, MCP-1, and MIP-1 beta were associated with decreased scores of mild cognitive impairment and higher CSF levels of neurodegenerative/PD-specific biomarkers in the total PD cohort." (PMID 37947613, 2023). "It has also been reported that intercellular adhesion molecule 1 (ICAM-1) and vascular adhesion molecule 1 (VCAM-1) were significantly upregulated in the vascular ECs of the CCH animal model associated with cognitive impairment." (PMID 34489623, 2021). "Interestingly, plasma levels of soluble VCAM1 increase with aging in both humans and mice and positively correlate with cognitive impairment, while ICAM1 shows only a mild effect." (PMID 41272813, 2025). "ICAM-1 and VCAM-1 were up-regulated in cerebral endothelial cells of CCH models, and the inhibition of ICAM-1 and VCAM-1 may protect cognitive impairment induced by chronic hypoperfusion." (PMID 35682903, 2022).
HIV-1 infection (15 papers, 1992 to 2025). The type species of lentivirus and the etiologic agent of acquired immunodeficiency syndrome (AIDS). "Breast milk contains high levels of soluble ICAM-1 (sICAM-1), which might inhibit cell-cell adhesion and modulate cell-associated HIV-1 infection." (PMID 22952771, 2012). "It remains to be determined what prevents the polybasic sequence of ICAM-1 from recruiting PIP2 in the context of HIV-1 infection." (PMID 40184445, 2025). "While ICAMs are not co-receptors for HIV-1 entry, the incorporation of host-derived ICAM-1 was shown to enhance HIV-1 infection in T and monocytic cells through enhanced physical interactions with LFA-1 on target cells." (PMID 30669528, 2019). "Additional evidence supporting the role of virus-incorporated ICAM-1 in HIV-1 infection include the diminished neutralizing activity of antibodies against Env and the ability of ICAM-1 antibodies to block virus entry." (PMID 22970312, 2012). "The virus-incorporated ICAM-1 markedly enhances HIV-1 infection of cells expressing LFA-1 by promoting the virus binding and internalization." (PMID 22970312, 2012). "Together, these findings imply that ICAM-1/LFA-1 interactions facilitate HIV-1 infection by enhancing the virus-cell binding." (PMID 22970312, 2012). "Together, these data suggest that ICAM-1 promotes HIV-1 infection by stabilizing the virus adhesion to LFA-1-positive cells without specifically enhancing the virus uptake or subsequent fusion with endosomes." (PMID 22970312, 2012). "A prominent example for such a factor is ICAM-1 which was found to be incorporated into the viral membrane, and to facilitate HIV-1 infection by binding to its ligand LFA-1 on T-cells." (PMID 20482880, 2010). "We report herein for the first time the detection of high levels of free circulating ICAM-1 in serum and cerebrospinal fluid of patients with HIV-1 infection." (PMID 18475479, 1992). "The blockade of ADAP-induced HIV-1 infection with soluble ICAM-1-Fc suggested that ADAP might contribute to integrin-mediated viral transmission via affecting the formation of VS and cell-cell conjugation." (PMID 24047317, 2013). "Previously, we demonstrated that ps20 enhanced HIV-1 infection through ICAM-1 modulation." (PMID 21545747, 2011). "Thus, while the importance of ICAM-1 in HIV-1 infection is notable, the effects of its cognate ligand, LFA-1, are also highly significant, as it is involved in mediating viral and immunological synapses that can increase the efficiency of cell-to-cell transmission." (PMID 30669528, 2019). "During HIV-1 infection, gamma interferon (IFN-γ)-mediated enhancement of ICAM-1 expression on the surface of ECs promotes the adhesion of HIV-1+ T cells to ECs and transendothelial migration." (PMID 35435723, 2022). "The interaction between ICAM-1 and LFA-1 is important in T cell activation, migration of T cells to target sites, and pertinent to HIV-1 infection, in the formation of syncytia." (PMID 30669528, 2019). "Soluble ICAM-1 and plasma ANG-2 levels represent potential biomarkers for adverse outcomes in advanced HIV-1 infection." (PMID 23734875, 2013). "Several genes have been established as important for HIV-1 infection and replication, including Pou2AF1 (OBF-1), complement factor H related 3, CD4 receptor, ICAM-1, NA, and cyclin A1." (PMID 15780141, 2005). "Comparing iMDDCs infected with CD45-depleted HIV-1BaL or matched non-depleted preparations, the presence of CD45+ MVs was shown to enhance DC maturation and ICAM-1 (CD54) expression, which is involved in DC∶T lymphocyte interactions, while restricting HIV-1 infection of MDDCs." (PMID 24204260, 2013). "As observed in both tables and the initial screening of genes displaying at least two present calls, several genes have been established as important for HIV-1 infection and replication, including OBF-1, complement factor H related 3, CD4 receptor, ICAM-1, NA, and cyclin A1." (PMID 15780141, 2005).
hyperlipidemia (15 papers, 2013 to 2025). "In studies with sea buckthorn berry extract, the polyphenols significantly reduced serum levels of TNF-α and IL-6 and also alleviated vascular impairment by decreasing the expression of eNOS and ICAM-1 in the aortas of rats with hyperlipidemia." (PMID 41156509, 2025). "A clinical study on patients with hyperlipidemia reported that cardiotonic pills significantly decreased ICAM-1 and E-selectin expression." (PMID 37111353, 2023). "Hence, we asked if ICAM-1 abundance was increased by hyperlipidemia and if it was reduced by intravenous NPC administration." (PMID 37715288, 2023). "During the early stages of hyperlipidemia, LPC triggers EC activation, leading to the production of ICAM-1." (PMID 39974277, 2025). "In the case of hyperlipidemia-induced oxidative stress and inflammation of heart, aloe-emodin significantly reduced the expression levels of proinflammatory cytokines (IL-1β, IL-6, and TNFα), as well as vascular cell adhesion molecule 1 (VCAM1) and intercellular adhesion molecule 1 (ICAM-1)." (PMID 35744949, 2022). "Although hyperlipidemia and disturbed blood flow can also promote NFκB activation and expression of inflammatory cytokines and leukocyte adhesion molecules, endothelial cell VE‐PTP deletion in ApoE−/−/VE‐PTPiECKO mice was not accompanied by changes in ICAM1 or VCAM1 in aortic endothelial cells." (PMID 36740996, 2023).
kidney damage (15 papers, 2013 to 2025). "ICAM-1 is a major downstream inflammatory factor, and an ICAM-1 gene deficiency presents a protective effect against nephropathy in type 2 diabetic db/db mice." (PMID 29621130, 2018). "ICAM-1 gene deficiency prevents nephropathy in type 2 diabetic db/db mice." (PMID 23718910, 2013). "Chronic inflammation, marked by transforming growth factor-β (TGF-β) and intracellular adhesion molecule-1 (ICAM-1) activity, contributes to kidney damage and fibrosis." (PMID 39727950, 2024). "Slow nicotine metabolizers exhibit lower levels of inflammation (ICAM-1 and PGEM) compared to fast metabolizers, which is linked to kidney damage." (PMID 39355620, 2024). "In fact, ICAM1 is upregulated upon kidney disease in all three groups of nephropathy samples, underscoring its importance in the context of kidney disease." (PMID 35806457, 2022). "In diabetic patients with nephropathy, the levels of ICAM-1 and MCP-1 recruiting inflammatory immune cells of macrophages and granulocytes were elevated." (PMID 25880429, 2015). "ICAM-1 expression would be upregulated under high glucose condition, which mediates the infiltration of inflammatory cells into renal glomeruli and results in kidney damage." (PMID 36923354, 2023). "In addition, we directly blocked leukocyte adhesion using anti-ICAM-1 antibodies to assess the pathophysiological implications of the leukocyte–endothelial interaction in salt-induced hypertension and kidney damage in Dahl S rats." (PMID 28298656, 2017). "This OTA-induced oxidative stress promotes an inflammatory response by upregulating the expression of NF-κB, intercellular adhesion molecule-1 (ICAM-1) and vascular cell adhesion molecule-1 (VCAM-1), contributing to kidney damage." (PMID 40423338, 2025). "Recent studies correlated the overexpression of pro-inflammatory (IL-1β, IL-6, TNF-α, and VEGF) and profibrotic genes (ICAM-1 and VCAM-1) with the appearance of nephropathies in diabetic patients." (PMID 36139749, 2022). "NF-κB activation can regulate the overexpression of adhesion molecules ICAM-1, FN, and other ECM components, leading to continuous inflammation and kidney damage." (PMID 33519473, 2020). "In this study, plasma concentration of ICAM-1 was elevated in microalbuminuric patients and in patients with overt nephropathy, plasma VCAM-1 was elevated only in patients with overt nephropathy." (PMID 26239462, 2015).
liver cancer (15 papers, 2017 to 2025). An epithelial or non-epithelial malignant neoplasm that arises from the liver. "A prospective cohort study of 282 patients with liver disease also demonstrated the association of soluble serum ICAM1 and liver cancer development." (PMID 34176789, 2021). "The α-fetoprotein (AFP) and soluble intercellular adhesion molecule-1 (sICAM-1) have certain diagnostic value, but their potential value in prognosis prediction, especially immunotherapy response prediction, remains unclear in liver cancer." (PMID 34696675, 2021). "The expression of liver cancer stem cell markers (ICAM1, CD47, CD24 and EPCAM) in HCC cells were determined by qPCR." (PMID 38169544, 2024). "A microarray study of liver cancer patients showed that ICAM1 axis is necessary for tumor immune evasion and the tumorigenesis of liver cancer." (PMID 34176789, 2021). "This study aimed to explore the clinical value of AFP and ICAM-1 to judge surgical prognosis and evaluate potential therapeutic effects for patients with liver cancer." (PMID 34696675, 2021). "In summary, our results indicated that MAPK10 abundance has a functional impact on the expression of the cell adhesion and costimulatory molecule ICAM1 in liver cancer cells possibly contributing to the MAPK10 immune effects in the TME." (PMID 34408980, 2021). "RNA-seq analysis revealed downregulation of the MAPK/ERK pathway through the downstream effectors ICAM1, leading to suppress tumor growth and increase chemosensitivity of liver cancer toward chemotherapy." (PMID 34176789, 2021). "Studies have also shown that ICAM-1 is a marker of human and mouse liver cancer stem cells and is involved in the metastasis of liver cancer cells." (PMID 32195055, 2020). "In addition, our previous study found that ICR (ICAM-1-related lncRNA), which is expressed in liver cancer stem cells (CSC), regulated CSC properties of ICAM-1+ HCC cells and promoted tumor cell migration." (PMID 35847364, 2022). "We thus hypothesized that MAPK10 may regulate ICAM1 expression in liver cancer cells by modulating the activity of AP-1TFs." (PMID 34408980, 2021). "Dysregulation of ICAM1 has been confirmed in liver cancer and ESCC stem cells." (PMID 33935718, 2021). "Intercellular Adhesion Molecule 1 (ICAM1) is an oncogene of liver cancer." (PMID 34176789, 2021). "It’s noteworthy that ICAM-1 and FGG expression is correlated with favorable prognostic in particular malignant tumors such as breast and liver cancer, suggesting diverse roles of ICAM-1–FGG signaling in different malignant cell development." (PMID 39168965, 2024). "In this NMA study, compared with ST alone, combined TCM can significantly reduce the expression of VEGF, ICAM-1, IL-6, and TGF-β levels, thus improving the immunity of liver cancer patients." (PMID 36118529, 2022). "Another clinicopathological study of 236 liver cancer patients suggested that ICAM promoted liver cancer metastasis and high serum ICAM1 level had shorter DFS and OS after resection in patients with liver cancer." (PMID 34176789, 2021). "Our data demonstrates that MAPK10 expression correlates with ICAM1 expression in the TME of HCC patients, and that MAPK10 is able to functionally influence ICAM1 gene expression in cultured liver cancer cells." (PMID 34408980, 2021). "Finally, we identified binding cites for the c-jun transcription factor in the promoter of the ICAM1 gene, and we found that the phosphorylation of c-jun at Ser63 is differentially regulated in MAPK10 overexpressing and knock-down liver cancer cells." (PMID 34408980, 2021). "We found, by using qPCR, that the expression of ICAM1 in MAPK10-overexpressing HepG2-MAPK10 cell line was significantly higher than in the control HepG2-puro cell line, suggesting that MAPK10 is able to promote the expression of the co-stimulatory molecule ICAM1 in liver cancer cells (P < 0.0001)." (PMID 34408980, 2021).